UTRN (utrophin)
Diseases named in the same sentence as UTRN in open-access papers (continued):
Sharing a sentence is not in itself a finding about the gene and the disease.
cardiomyopathy (9 papers, 2015 to 2025). A disease of the heart muscle or myocardium proper. "Supporting this, Cldn5 was significantly downregulated at the cardiomyocyte lateral membrane in a dystrophin–utrophin double knockout (Dmdmdx;Utrn−/− dko) mouse model that recapitulates features of cardiomyocyte degeneration and myocarditis, implicating Cldn5 loss in cardiomyopathy pathogenesis." (PMID 40940757, 2025). "A full-length human utrophin transgene expressed from a skeletal muscle-restricted promoter/enhancer (Tg(ACTA1-Utrn)2Ked; “Fiona”) was used to rescue the skeletal muscle pathology of dystrophin/utrophin-deficient mice (utrn–/– mdx; dko), allowing progression of cardiomyopathy (Fiona/dko)." (PMID 33651713, 2021). "Loss of utrophin (UTRN) was involved in the advancement of cardiomyopathy, but this gene may be liable for progression of CAD." (PMID 31881747, 2019). "Approaches that can elicit expression of full-length utrophin, such as small drug treatment, in dystrophin-deficient hearts may have a clinically meaningful impact on the cardiomyopathy of DMD patients." (PMID 30417024, 2018). "Another potential mechanism by which microdystrophin expression leads to cardiomyopathy, potentially in combination with utrophin displacement, is the saturation of the UPS by the excess microdystrophin molecules." (PMID 38713520, 2024). "For instance, despite similar expression levels between MCD2 and MCD4, the latter both hastens onset of cardiomyopathy and displaces utrophin to a larger extent." (PMID 38713520, 2024). "The acceleration of the cardiomyopathy is coincident with the efficient displacement of utrophin by 2 of the microdystrophins (MDC1 and MDC4)." (PMID 38713520, 2024). "Expression of only 11 genes, in addition to utrophin, differ between mdx and dko hearts at cardiomyopathy onset, and 10 of these are in proinflammatory and profibrotic pathways known to be markers for human cardiomyopathy." (PMID 33651713, 2021). "In the Dystrophin−/− (Dmd1)/Utrophin−/− (Utrn) cardiomyopathy model, Cldn5 mRNA and protein levels decline; in contrast, Cldn5 overexpression diminishes cardiomyopathy in Dmd1−/−:Utrn−/− mice." (PMID 31174463, 2019). "A recent publication demonstrated that increasing utrophin expression via an alternative pharmacological approach protects the mdx mice against cardiomyopathy." (PMID 25935002, 2015). "We present the data and observations in support of the first mechanism (utrophin displacement) as the main contributor to microdystrophin-induced acceleration of cardiomyopathy and to overload of the UPS occurring if the expression levels are high enough (as with MDC1)." (PMID 38713520, 2024). "The premature onset of this cardiomyopathy appears to be related to the extent of microdystrophin overexpression in the heart and the specific design of the microdystrophin that alters its competition with utrophin for binding to the DGC." (PMID 38713520, 2024). "However, in both dystrophin-deficient and dystrophin/utrophin-deficient hearts, the DGC remains localized to cardiomyocyte membranes, despite that mutations of some DGC members also lead to cardiomyopathy." (PMID 33651713, 2021). "We have previously demonstrated that WBPA-elicited NO production alleviated the cardiomyopathy’s severity in mice lacking both dystrophin and utrophin protein expression." (PMID 34017265, 2021).
Becker muscular dystrophy (3 papers, 2016 to 2025). Becker muscular dystrophy (BMD) is a neuromuscular disease characterized by progressive muscle wasting and weakness due to degeneration of skeletal, smooth and cardiac muscle. "It has been also shown that DMD and Becker muscular dystrophy (BMD) patients express abnormally high levels of utrophin, similar to what we observed in LV tissue samples of Dmdmdx compared to wt rats." (PMID 33619211, 2021). "We quantified sarcolemmal utrophin in mature and regenerating fibres and the percentage of regenerating muscle fibres, in muscle biopsies from Duchenne, the milder Becker muscular dystrophy and controls." (PMID 26974331, 2016). "This will be valuable information if the same mechanism is shown to be present in human adult skeletal muscle, considering the important role that utrophin production could have on Duchenne and Becker muscular dystrophies patients." (PMID 40224962, 2025).
breast carcinoma (3 papers, 2011 to 2024). "This research provides a novel perspective on UTRN’s role in breast cancer’s prognostic and therapeutic value." (PMID 38565593, 2024). "In summary, UTRN plays a role in breast cancer carcinogenesis, progression, and response to endocrine therapy." (PMID 38565593, 2024). "In humans, however, defective expression of utrophin because of UTRN mutations has been detected in various types of human tumors, such as breast cancers, neuroblastomas, and malignant melanomas." (PMID 35790299, 2022). "However, UTRN’s function in the response to endocrine therapy and its role in the tumor immune microenvironment in breast cancer remain unexplored." (PMID 38565593, 2024). "Moreover, UTRN downregulation has been observed in breast cancer, with in vitro UTRN overexpression inhibiting tumor cell development." (PMID 38565593, 2024). "Notably, it is also proposed as a TS candidate as the UTRN gene has been found to be mutated in human cancers, like breast cancers, neuroblastomas, and malignant melanomas and as overexpression of utrophin in breast cancer cells inhibits growth." (PMID 35790299, 2022). "Moreover, utrophin, the highly related autosomal paralogue of dystrophin, represents a tumor suppressor candidate, owing to its frequent disruption in human malignant tumors and its capability to inhibit breast cancer cell growth." (PMID 21533183, 2011).
progressive muscular dystrophy (3 papers, 2017 to 2021). "The dystrophin–utrophin knockout (dKO) model presents with a severe phenotype that closely recapitulates disease in patients, specifically severe progressive muscular dystrophy, premature death and a plenitude of physiological and molecular aberrations." (PMID 34389686, 2021).
Ewing sarcoma (2 papers, 2015 to 2021). A small round cell tumor that lacks morphologic, immunohistochemical, and electron microscopic evidence of neuroectodermal differentiation. "Of particular relevance, UTRN (Utrophin) was significantly upregulated in Ewing sarcoma cell lines but repressed in osteosarcoma cell lines (P = 0.025)." (PMID 26095524, 2015).
malignant melanomas (2 papers, 2021 to 2022). "Herein, we studied the function of UTRN in melanoma growth and the relevant molecular mechanisms." (PMID 33632212, 2021). "Collectively, this work discovered that UTRN could act as a tumor suppressor gene in melanoma and serve as a prognostic factor." (PMID 33632212, 2021). "In addition, p38 and JNK/c-Jun signaling pathways were the key biological mechanisms regulated by UTRN in melanoma." (PMID 33632212, 2021). "In addition, up-regulated utrophin expression inhibited melanoma cell proliferation." (PMID 35790299, 2022).
schizophrenia (2 papers, 2019 to 2020). A major psychotic disorder characterized by abnormalities in the perception or expression of reality. "UTRN encodes for utrophin, which is located at synapse and myotendinous junctions, and was reported to be a candidate gene for schizophrenia and BD." (PMID 31118907, 2019).
cardiac hypertrophy (1 paper, 2022). "ERK1/2 activation protects myofibers from damage and contributes to cardiac hypertrophy and protein expression of dystrophin and utrophin in skeletal muscle." (PMID 35065666, 2022).
dilated cardiomyopathy (1 paper, 2025). Cardiomyopathy which is characterized by dilation and contractile dysfunction of the left and right ventricles. "The overexpression of micro-dystrophin in cardiac tissue may also lead to adverse outcomes, like dilated cardiomyopathy, possibly due to competition with endogenous utrophin or protein degradation overload." (PMID 40332074, 2025). "However, studies have identified potential risks associated with excessive micro-dystrophin expression in the heart, which may lead to dilated cardiomyopathy and heart failure due to competition with native utrophin and protein degradation pathway overload." (PMID 40332074, 2025).
fibrosis (1 paper, 2015). the formation of excess fibrous connective tissue in an organ or tissue in a reparative or reactive process. "Thus, the improvement of muscle functions observed in both young and old mdx mice after anti-fibrosis treatment was probably due to the combined effects of reduced fibrosis, increased utrophin levels, and increased numbers of RFs." (PMID 26015394, 2015).
Hypertension (1 paper, 2015). The presence of chronic increased pressure in the systemic arterial system. "Unlike glucocorticoids, ApN increases insulin sensitivity, does not induce muscle atrophy but rather reduces proteolysis, upregulates utrophin (our own data) and enhances the myogenic program, prevents obesity, and protects against hypertension." (PMID 26257862, 2015).
Immunodeficiency (1 paper, 2006). Failure of the immune system to protect the body adequately from infection, due to the absence or insufficiency of some component process or substance. "Our data also supports the fact that immunodeficiency is correlated with altered calcium ion binding (UTRN, ID: AA676840; CDH6, ID: AA421819, CASQ2, ID: AA055163) and also is influenced by calcium- activated chloride channels (CLCA2, ID: AI675394) of host cells." (PMID 16956415, 2006).
Infertility (1 paper, 2017). "Although the results suggest the involvement of dystrophin and utrophin during the development of male reproductive organs, the contribution of utrophin in mdx/utrn+/− mouse infertility needs further investigation." (PMID 28785010, 2017).
Insulin resistance (1 paper, 2021). Increased resistance towards insulin, that is, diminished effectiveness of insulin in reducing blood glucose levels. "Hence, the effect of stabilized utrophin on adipose tissues and insulin resistance could be an interesting research direction for further investigation." (PMID 34454586, 2021).
migraine (1 paper, 2020). "We also identified five RLS‐associated SNPs (rs2858654, rs76770509, rs150762626, rs2668375, and rs4243475 in UTRN, which encodes utrophin) in individuals with migraine, especially MoA." (PMID 32918390, 2020).
respiratory failure (1 paper, 2025). The significant impairment of gas exchange within the lungs resulting in hypoxia, hypercarbia, or both, to the extent that organ tissue perfusion is severely compromised. "In utrophin-deficient mdx mice (mdx/utrn double knockout mice), a much more severe phenotype is observed, including growth retardation, weight loss, spinal curvature, and premature death due to respiratory failure at around 20 weeks." (PMID 40940738, 2025).
retinal detachment (1 paper, 2009). An eye emergency condition which may lead to blindness if left untreated. "Retinal detachment induced an increase of utrophin immunolabeling in the inner limiting membrane (arrow and arrowhead)." (PMID 19809515, 2009).
rheumatoid arthritis (1 paper, 2020). A chronic, systemic autoimmune disorder characterized by inflammation in the synovial membranes and articular surfaces. "Furthermore, other reported AhR antagonists also upregulate utrophin, showing that this pathway, which is currently being explored in other clinical applications including oncology and rheumatoid arthritis, could also be exploited in future DMD therapies." (PMID 31755636, 2020).
sarcoglycanopathies (1 paper, 2011). "However, some cases of BMD may not show sarcolemmal utrophin, while occasional sarcoglycanopathies may show utrophin expression." (PMID 21798100, 2011).
tumor (13 papers, 2011 to 2025). "In the female cohorts, the downregulated proteins, such as utrophin, Rab-8B, and eS8, were associated with protein synthesis, while many upregulated proteins were linked to tumor progression." (PMID 41154628, 2025). "This added to existing knowledge that the UTRN gene, which codes for the dystrophin-related protein utrophin, also acts as a tumour suppressor." (PMID 33188621, 2021). "UTRN functions as a tumor suppressor gene and impacts the growth of various malignancies." (PMID 38565593, 2024). "Fourteen of the mutated genes in this tumor are involved in metabolism (endogenous molecules as well as drugs), small molecule biochemistry, and cancer: AATF, ATF71P, CRIPAK, CROCC, CYP2A6, DOCK5, GPAT2, KRTAP4–9, LSM14A, MUC2, MYO1F, RHOQ, SUFU, and UTRN." (PMID 29259192, 2017). "Utrophin (UTRN), known as a tumor suppressor, potentially regulates tumor development and the immune microenvironment." (PMID 38565593, 2024). "Results showed that the expression of five parent gene (PRIM2, ABCC4, UTRN, ABHD2, and MTHFD2L) was also significant increase in tumor compared to those in normal tissues." (PMID 34852706, 2021). "We found three down-regulated genes/proteins discriminating BIC-resistant cell lines from LNCaP cells: ADAMTS1, identified as a possible tumor suppressor and two cell adhesion proteins involved in PCa progression, NCAM2 and UTRN." (PMID 29216878, 2017). "The influence of histone genes on tumor developments might be supported by the eQTLs identified in the current study, because some of the eQTLs were located within anticipated tumor suppressor genes such as low-density lipoprotein receptor-related protein (LRP1B) and utrophin (UTRN)." (PMID 28929106, 2017).
cancer (8 papers, 2011 to 2022). A tumor composed of atypical neoplastic, often pleomorphic cells that invade other tissues. "We previously found that TAPP2, in association with the F-actin-binding proteins utrophin and syntrophin, functions in the firm adhesion of BCR- or SDF-1-activated cancer B cells to extracellular matrix proteins." (PMID 23460911, 2013). "However, the associations of other genes used in our model with ICI efficacy have not been reported, although some of them have been found to play critical roles in cancer, such as COL5A2, FAT2, ITPR3, PCDH20, and UTRN." (PMID 35557959, 2022). "Utrophin (UTRN), as a tumor suppressor gene, is involved in various cancer progression." (PMID 33632212, 2021). "Panobinostat, a non-selective HDAC inhibitor for cancer treatment, increased utrophin levels by 1.9-fold." (PMID 32034254, 2020).
neuromuscular disease (1 paper, 2020). "Therefore, we speculated that dysfunction of utrophin was involved in other neuromuscular diseases, including RLS." (PMID 32918390, 2020).
peripheral neuropathy (1 paper, 2020). A disorder affecting the peripheral nervous system. "Indeed, specific dystrophin (Dp116) and utrophin are the major subtypes of dystrophins in Schwann cells; furthermore, Duchenne MD patients with Dp116 deficiency have no apparent peripheral neuropathy." (PMID 32453729, 2020).
UTRN also shares sentences with these, for which no sentence is quoted: amyotrophic lateral sclerosis (3 papers); inflammatory myopathies (2); osteosarcoma (2); spinal muscular atrophies (2); attention deficit-hyperactivity disorder (1); autism spectrum disorder (1); autosomal recessive limb-girdle muscular dystrophy type 2D (1); bipolar disorder (1); bladder urothelial cancer (1); cognitive deficits (1); congenital myopathies (1); diabetic neuropathies (1); dystroglycanopathies (1); eating disorder (1); endothelial dysfunction (1); heart failure (1); infection (1); lung carcinoma (1); major depressive disorder (1); mental disorder (1); myocarditis (1); myotonic dystrophy type 1 (1); neuroblastoma (1); Obesity (1); of muscle (1); thalassemia (1).